FAP (fibroblast activation protein alpha)
Diseases named in the same sentence as FAP in open-access papers (continued):
Sharing a sentence is not in itself a finding about the gene and the disease.
prostate carcinoma (47 papers, 2015 to 2026). A carcinoma that arises from epithelial cells of the prostate gland. "In prostate cancer, the infiltration of regulatory T cells (Tregs) was associated with an immunosuppressive microenvironment in advanced disease, possibly induced by a FAP+ fibroblast subpopulation." (PMID 39759507, 2024). "For example, prostate carcinoma-secreted IL-6 can increase the expression of the cancer-associated fibroblast marker FAP, activating human prostate fibroblasts and enhancing the invasive ability of prostate cancer." (PMID 37821959, 2023). "Nonetheless, in the light of the deficient data availability on FAP function in prostate cancer this study represents a first glimpse at the putatively complex interactions." (PMID 34854061, 2022). "Intratumoral injections of a newly synthesized FAP-activated protoxin caused cell lysis of FAP+ CAFs and reduced tumor growth in breast and prostate cancer xenografts." (PMID 36671452, 2022). "Interestingly, across all three prostate cancer cohorts, we observed a consistent association between leukocyte cluster density and epithelial FAP expression, while stromal FAP showed weaker or cohort‐dependent associations." (PMID 41410015, 2026). "Additionally, we found that stromal FAP is positively associated with Gleason Grade, indicating that higher FAP levels correlate with more clinically significant tumours in prostate cancer." (PMID 41410015, 2026). "In addition, FAP+CAFs are associated with the invasion of high-grade invasive uroepithelial carcinoma of the bladder, invasion and proliferation of prostate cancer, and infiltration depth of esophageal cancer." (PMID 37277751, 2023). "This hampers the diagnostic relevance of FAP in early prostate cancer." (PMID 34854061, 2022). "FAP overexpression leads to a higher risk of tumor invasion, lymph node metastasis and to decreased overall survival (OS) and has been shown to be expressed in various cancers including prostate cancer, as well as chronic inflammatory diseases with fibrotic changes." (PMID 34854061, 2022). "Furthermore, a FAP-activated prodrug derived from thapsigargin (a highly toxic natural plant product that stimulates increased intracellular calcium levels to cause apoptosis) is also reported to decrease tumor burden in LNCaP prostate cancer xenografts." (PMID 36671452, 2022). "We developed an AI‐based image analysis pipeline for automated quantification of FAP and αSMA expression in prostate cancer TMAs stained using a dual‐chromogen IHC protocol." (PMID 41410015, 2026). "Our study validates the significance of FAP as a prognostic tissue biomarker in prostate cancer (PCa) using an AI‐based image analysis model." (PMID 41410015, 2026). "The model was trained to perform tissue compartment‐specific detection of FAP and αSMA, as well as leukocyte infiltration, in digitised high‐resolution images from three prostate cancer tissue microarray (TMA) cohorts." (PMID 41410015, 2026). "The multi‐spheroid model consists of prostate stem cell antigen (PSCA)‐expressing prostate cancer cells and FAP‐producing fibrosarcoma cells in varying ratios." (PMID 40704837, 2025). "Towards this aim, we employed CWR-R1FAP cells, a castration-resistant prostate cancer cell line with stable heterologous FAP expression, as well as parental FAP-null CWR-R1 cells." (PMID 39868181, 2025). "As a biochemical cue, the impact of fibroblast activation protein (FAP), an emerging target in the tumor microenvironment, is investigated on prostate cancer spheroids and on the efficacy of CAR T cell therapy." (PMID 40704837, 2025). "This correlation further validates the specificity of Al18F-NOTA-FAP-2286 for FAP expression in acquired drug-resistant prostate cancer tumors." (PMID 40430845, 2025).
prostate carcinoma (continued). "From these datasets, we extracted gene expressions, including FOLH1, GRPR, FAP, and Harris Hypoxia, and estimated the proportions of different cell types—epithelial, endothelial, and prostate cancer (PC) cells—in the corresponding ST spots." (PMID 39629134, 2024). "Here, we aim to synthesize two bispecific tracers targeting prostate-specific membrane antigen (PSMA) and fibroblast activation protein (FAP), which are key markers expressed in prostate cancer." (PMID 38398552, 2024). "Initial applications of FAP-targeted imaging radioligands in prostate cancer patients, particularly those with low PSMA expression, have shown promising results." (PMID 39207485, 2024). "In a critical extension of this work, mice were subcutaneously injected with hPrCSC-44 (an immortalized human prostate cancer stromal cell line) in combination with DU145 (a FAP-null prostate cancer cell line) to establish a xenograft mouse model." (PMID 38543239, 2024). "This antibody serves as a FAP-expressing tumor-selective imaging probe for PET/CT imaging in a preclinical prostate cancer xenograft model." (PMID 38543239, 2024). "One strategy to improve lesion detection in this patient cohort is using bispecific radioligands to target PSMA and other overexpressed proteins in prostate cancer lesions, such as fibroblast activation protein (FAP)." (PMID 38398552, 2024). "FAP has been identified by genomic and immunohistochemical analyses as a target structure for imaging the tumour microenvironment in prostate cancer." (PMID 39207485, 2024). "FAP, which occurs predominantly in the tumour stroma, appears to be a potential marker for a more aggressive course and shorter survival in prostate cancer, similar to 2-[18F]FDG." (PMID 39207485, 2024). "The investigative process commenced with genomic and immunohistochemistry assessments to determine the expression of FAP in prostate cancer." (PMID 38543239, 2024). "Further investigations are needed to optimize the selection of linkers and targeted pharmacophores to improve the tumor uptake of bispecific PSMA/FAP tracers for prostate cancer imaging." (PMID 38398552, 2024). "In vitro and in vivo studies demonstrated 68Ga-iFAP-specific recognition for FAP, rapid renal elimination, and adequate visualization of the glioblastoma, breast tumor, prostate cancer, and myocardial infarction sites." (PMID 38675193, 2024). "Further investigations are needed to optimize the linker selection to generate promising bispecific PSMA/FAP-targeting tracers for prostate cancer imaging." (PMID 36770755, 2023). "The PC3 and U87MG subcutaneous xenografts were used because of their modest tumor growth and the abundant FAP expression in the stroma of human prostate carcinomas and glioblastomas." (PMID 37284857, 2023). "Both PSMA and FAP are promising biomarkers of prostate cancer and many radioligands have been developed to target these two membrane proteins for imaging and therapy." (PMID 36770755, 2023). "Of note, prostate cancer metastases from the Dream Team cohort also displayed relatively high correlation coefficients of FAP with FLT1 and KDR—thereby potentially mirroring the importance of angiogenesis in high-risk prostate cancer, as previously reported." (PMID 36672341, 2023). "Although FAP has been reported to be a useful target for diagnostics and therapy in various cancers, its use in prostate cancer seems however debatable." (PMID 34854061, 2022). "FAP-expressing CAFs have been detected in multiple epithelial tumors, including prostate cancer, and have also been explored as a therapeutic target." (PMID 36671452, 2022). "In this study we aimed to investigate the usefulness of FAP as a target for immunohistochemistry (IHC), imaging and subsequent theranostic approaches in prostate cancer besides PSMA." (PMID 34854061, 2022).
prostate carcinoma (continued). "YAP1 was upregulated in prostate cancer tissue, and FAP and α-SMA expression were significantly elevated in stromal and epithelial cells with high YAP1 expression levels, demonstrating the association between YAP1 and CAF development." (PMID 33808627, 2021). "FAP is a cell–surface serine protease detected in the stroma of different human epithelial cancers, including the stroma of prostate cancer." (PMID 34067049, 2021). "In contrast, ASPN+FAP− cells were as equally enriched as ASPN+FAP+ cells in the microenvironment adjacent to cribriform prostate cancer." (PMID 33600062, 2021). "Despite this interpatient heterogeneity, the collective percentage of FAP+ cells and the expression per positive cell was significantly enriched in the tumor microenvironment adjacent to Gleason grade 4 cribriform prostate cancer compared to benign prostate." (PMID 33600062, 2021). "Another interesting experimental approach is to target the prostate cancer stroma with a fibroblast activation protein-activated (FAP-activated) promelittin protoxin." (PMID 34067049, 2021). "The percent FAP+ cells in the stroma adjacent to Gleason grade 4 cribriform prostate cancer was highly heterogeneous among patients, with an approximate range between 5 and 50% positive." (PMID 33600062, 2021). "Moreover, imaging techniques targeting fibroblast activation protein (FAP) have shown significant promise in tumor diagnosis, particularly in metastatic cancers such as prostate cancer." (PMID 40093895, 2025). "Importantly, this affirmed FAP’s utility as a target imaging and therapeutic intervention within the prostate cancer tumor microenvironment." (PMID 38543239, 2024). "Since scRNA-seq analysis revealed that αSMA+ CAV1+ and FN1+ FAP+ CAFs were the two most abundant subpopulations of CAFs in prostate cancer microenvironment, we thus stained prostate cancer samples with these four fibroblasts markers to verified our findings from the bioinformatic analysis." (PMID 37033924, 2023). "To overcome this limitation and improve lesion detection sensitivity, we developed and evaluated three bispecific radiotracers that can target both prostate-specific membrane antigen (PSMA) and fibroblast activation protein (FAP), which are the two key proteins overexpressed in prostate cancer." (PMID 36770755, 2023). "While PSMA staining intensity is a valid indicator of prostate cancer in both primary tumor and lymph node metastases, the expression of FAP seems to be heterogeneous but not necessarily linked to cancer-associated fibroblasts." (PMID 34854061, 2022). "As up to date only few patients underwent FAP-PET, it might be too early to draw conclusions about the usefulness of FAP-PET in prostate cancer." (PMID 34854061, 2022). "Over 90% of epithelial tumors express FAP, including prostate cancer." (PMID 34854061, 2022). "Other enzymes than FAP, which are prostate cancer specific, may be used to activate a modified protoxin of melittin, as well." (PMID 34067049, 2021). "Other enzymes than FAP, which are prostate cancer specific, may also be used to activate a modified protoxin of melittin." (PMID 34067049, 2021). "The experience of FAP-specific PET in prostate cancer is very limited." (PMID 32942573, 2020). "Hence, by targeting PSMA, which is overexpressed in cancer cells, and FAP, which is overexpressed in tumor stroma, we hypothesized that it would potentially increase the lesion detection rate and tumor retention in prostate cancer patients." (PMID 38398552, 2024). "Furthermore, FAP targeted imaging aids to reveal the presence of additional primary tumors as has been shown in a case of newly diagnosed PSMA-negative metastatic gastric signet-ring cell carcinoma in a patient with known PSMA-positive prostate cancer." (PMID 34854061, 2022). "However, the role of FAP in prostate cancer diagnosis remains subject to further investigations." (PMID 34854061, 2022).
prostate carcinoma (continued). "In case of prostate cancer FAP might, therefore, aid to proper down- or upstaging of tumors." (PMID 34854061, 2022). ", it is currently unknown at which stage exactly FAP expression evolves in prostate cancer and to which extend it correlates to tumor load and aggressiveness, although a positive correlation of FAP expression has been detected with advancing prostate cancer, being highest im CRPC." (PMID 34854061, 2022). "In prostate cancer, FAP+ stromal programmes co‐occur with immunosuppressive myeloid states (e.g., CD163+/SPP1+ macrophages) and FAP itself can also promote macrophage activation and tissue remodelling." (PMID 41410015, 2026). "In cribriform prostate cancer, a specific subtype of CAFs characterized by the CTHRC1+ASPN+FAP+ENG+ signature was referred to as "CAFÉ CAFs", which was associated with an immunosuppressive TME." (PMID 39780187, 2025). "Relative to benign prostatic hyperplasia, stromal YAP1, FAP, and α-SMA levels were higher in prostate cancer, with substantial spatial overlap between YAP1 staining and the CAF marker FAP." (PMID 41514658, 2025). "Utilizing ST data from prostate cancer tissue, we simulated PSMA, FAP, and GRPR-targeted RPTs with both beta- and alpha- emitting ligand accounting for the complex heterogeneities within the TME." (PMID 39629134, 2024). "For high-grade prostate cancer (HG-PCa), the smMIP-method identified 8 markers, and the microarray identified 17 markers, with FOLH1, FAP and CLDN3 being common across both platforms." (PMID 39595976, 2024). "With the recent success of PSMA ligands in prostate cancer (e.g., [177Lu]Lu-PSMA-617), many investigators have put their attention to the development of FAP tracers." (PMID 36813980, 2023). "We discovered two major CAFs subtypes in prostate cancer microenvironment, termed αSMA+ CAV1+ CAFs-C0 and FN1+ FAP+ CAFs-C1." (PMID 37033924, 2023). "We identified two major CAFs subtypes with distinct molecular characteristics and biological functions in prostate cancer microenvironment, namely αSMA+ CAV1+ CAFs-C0 and FN1+ FAP+ CAFs-C1." (PMID 37033924, 2023). "In the present study, the use of FAP-based histopathological examination of malignant and benign prostate specimen as well as FAP-PET imaging in patients with prostate cancer have been investigated in two small patient collectives." (PMID 34854061, 2022). "The aim of this study was to compare FAP and Prostate-specific membrane antigen (PSMA) expression in primary prostate cancer employing histological analyses and PET imaging in two small patient collectives." (PMID 34854061, 2022). "Comparison of 177Lu-FAP-2286 to other radiopharmaceuticals previously reported to be effective (i.e., 177Lu-DOTATATE for neuroendocrine tumors and 177Lu-PSMA-617 for prostate cancer) shows comparable absorbed doses for whole body, bone marrow, and kidneys." (PMID 34168013, 2022). "While CTHRC1+ CAF were slightly elevated, ASPN+ and FAP+ CAF were comparable between ICC/IDC and Gleason pattern 5 prostate cancer." (PMID 36229464, 2022). "Overall, FAP+ cells and THY1+ cells were enriched in the microenvironment of Gleason grade 4 cribriform prostate cancer compared to stroma adjacent to benign prostate." (PMID 33600062, 2021). "Similar to FAP, the percentage of THY1+ cells was heterogeneous in stroma adjacent to cribriform prostate cancer." (PMID 33600062, 2021). "Most recently, a family of quinoline-based positron emission tomography (PET)/computed tomography (CT) tracers were derived from a FAP inhibitor (FAPI) and demonstrated promising uptake in multiple cancer entities, including prostate cancer (PC)." (PMID 34226953, 2021). "Interestingly, knockdown of FAP in cancer cells also led to reduced cell proliferation, invasion, and metastasis in oral squamous cell carcinoma (OSCC) and prostate cancer." (PMID 39780187, 2025).
prostate carcinoma (continued). "We performed an in vitro competition binding assay, PET imaging, and ex vivo biodistribution studies in preclinical PSMA-expressing LNCaP and FAP-expressing HEK293T:hFAP tumor models to evaluate the potential of [68Ga]Ga-AV01084 and [68Ga]Ga-AV01088 for prostate cancer imaging." (PMID 38398552, 2024). "Their potential of the tracers for prostate cancer imaging was evaluated by an in vitro competition binding assay, PET imaging, and ex vivo biodistribution studies in preclinical PSMA-expressing LNCaP and FAP-expressing HEK293T:hFAP tumor models in mice." (PMID 36770755, 2023). "In terms of prostate cancer, the role of FAP has not been fully investigated yethowever it seems to have potentially beneficial features for diagnosis through imaging in prostate-specific membrane antigen (PSMA)-negative or -low disease." (PMID 34854061, 2022). "The overall FAP H‐score was significantly higher in Gleason grade 4 cribriform prostate cancer compared to Gleason grade 4 prostate cancer with noncribriform morphologies, Gleason grade 3 prostate cancer, and benign prostate." (PMID 33600062, 2021). "As FAP was prognostic only in patients with tumors classified as MRI positive, but not MRI negative, the findings suggest that FAP could be a relevant biomarker of prostate cancer progression, especially when combined with MRI diagnostics." (PMID 36874403, 2022). "Patient A2 showed FAP expression in prostate cancer tissue, but not in LN specimen." (PMID 34854061, 2022). "No dedicated study on FAP-specific PET for target volume delineation in prostate cancer could be found." (PMID 32942573, 2020). "However, two hypotheses that have to be investigated further evolved: first, FAP expression alone may be not useful for early and initial diagnosis of prostate cancer as it is unspecific and found in multiple conditions." (PMID 34854061, 2022). "Patients with proven prostate cancer infiltration exhibited strong positivity for PSMA in both primary tumors and lymph node metastases while stainings for FAP were found positive in some cases, but not all (2/5)." (PMID 34854061, 2022). "CTHRC1+, ASPN+, and FAP+ CAF were located peri-epithelial to ICC/IDC and were significantly enriched in ICC/IDC compared to benign prostate as well as Gleason pattern 3 and Gleason pattern 4 non-ICC prostate cancer." (PMID 36229464, 2022).